IL13 (interleukin 13)
Description:
Cytokine that plays important roles in allergic inflammation and immune response to parasite infection. Synergizes with IL2 in regulating interferon-gamma synthesis. Stimulates B-cell proliferation, and activation of eosinophils, basophils, and mast cells. Plays an important role in controlling IL33 activity by modulating the production of transmembrane and soluble forms of interleukin-1 receptor-like 1/IL1RL1 (By similarity). Displays the capacity to antagonize Th1-driven proinflammatory immune response and downregulates synthesis of many proinflammatory cytokines including IL1, IL6, IL10, IL12 and TNF through a mechanism that partially involves suppression of NF-kappa-B (By similarity). Also functions on nonhematopoietic cells, including endothelial cells where it induces vascular cell adhesion protein 1/VCAM1, which is important in the recruitment of eosinophils. Exerts its biological effects through its receptors which comprises the IL4R chain and the IL13RA1 chain, to activate JAK1 and TYK2, leading to the activation of STAT6. Aside from IL13RA1, another receptor IL13RA2 acts as a high affinity decoy for IL13 and mediates internalization and depletion of extracellular IL13. Induces inflammatory response in esophageal epithelium which results in a dysregulation of desmosome intercellular adhesion junctions, via down-regulation of DSG1.
Synonyms: IL-13; P600; ALRH; BHR1; MGC116786; MGC116788; MGC116789
Tractability: Small molecule: it has a high-quality binding pocket. Antibody: an approved drug acts on it; its Gene Ontology location is reachable by antibodies, with high confidence; UniProt places it where antibodies can reach, with medium confidence; UniProt predicts a signal peptide or a membrane-spanning region.
Target class: Secreted protein
Safety:
Unwanted effects reported when the protein is acted on. In parentheses: how it was acted on, where the effect was seen, and who reports it.
drug toxicity (source: ClinPGx)
Gene: Protein-coding gene on chromosome 5 (132,656,263 to 132,661,110, forward strand). Ensembl gene ENSG00000169194.
Subcellular location: Secreted
Pathways (Reactome):
Immune System: Interleukin-18 signaling; Interleukin-4 and Interleukin-13 signaling
Developmental Biology: Differentiation of naive CD4+ T cells to T helper 2 cells (Th2 cells)
Gene Ontology:
Molecular function: cytokine activity; protein binding; interleukin-13 receptor binding; cytokine receptor binding
Biological process: cell surface receptor signaling pathway via JAK-STAT; interleukin-13-mediated signaling pathway; macrophage activation; negative regulation of complement-dependent cytotoxicity; negative regulation of endothelial cell apoptotic process; negative regulation of inflammatory response; positive regulation of inflammatory response; positive regulation of interleukin-10 production; positive regulation of transcription by RNA polymerase II; positive regulation of tyrosine phosphorylation of STAT protein; apoptotic process; ERK1 and ERK2 cascade; inflammatory response; negative regulation of lung ciliated cell differentiation; positive regulation of cold-induced thermogenesis; positive regulation of ERK1 and ERK2 cascade; positive regulation of gene expression; positive regulation of immunoglobulin production; positive regulation of lung goblet cell differentiation; regulation of transforming growth factor beta1 production; transforming growth factor beta1 production; cellular response to mechanical stimulus; immune response; microglial cell activation; negative regulation of transforming growth factor beta production; and 12 more
Cellular component: extracellular region; interleukin-13 receptor complex; plasma membrane; receptor complex; cytoplasm; external side of plasma membrane
Genetic constraint (gnomAD): Loss-of-function variants: 8 observed, 10.55 expected, observed/expected ratio (o/e) 0.76, 90% interval 0.44 to 1.36. The upper end of that interval is the gene's LOEUF score, 1.36, which puts it in group 5 of 6, group 1 being the genes least tolerant of losing a copy. Missense variants: 102 observed, 118.14 expected, observed/expected ratio (o/e) 0.86, 90% interval 0.74 to 1.02. Synonymous variants: 40 observed, 45.82 expected, observed/expected ratio (o/e) 0.87, 90% interval 0.68 to 1.14.
Homologues: Orthologues: chimpanzee IL13 (98% identical), macaque IL13 (95% identical), pig IL13 (68% identical), dog IL13 (64% identical), rabbit IL13 (60% identical), guinea pig IL13 (59% identical), rat Il13 (53% identical), mouse Il13 (51% identical).
Diseases named in the same sentence as IL13 in open-access papers:
IL13 is named in the same sentence as 709 diseases in open-access papers, as found by Europe PMC text mining. Sharing a sentence is not in itself a finding about the gene and the disease. The quoted sentences say what the papers report.
asthma (1,877 papers, 2004 to 2026). "Genetic polymorphisms in interleukin-13 (IL13) gene have been associated with asthma susceptibility in different ethnicities." (PMID 39744511, 2025). "For example, gene variations associated with the IL-4/IL-13 pathway are linked to asthma susceptibility." (PMID 40313547, 2025). "Interleukin-13 (IL-13): This cytokine has a complex role in asthma and is especially associated with airway remodeling and mucus overproduction." (PMID 40564060, 2025). "By inhibiting IL-4 and IL-13 signaling pathways, dupilumab addresses key mechanisms underlying asthma pathophysiology." (PMID 40564060, 2025). "T helper cell 2, i.e., Type 2 (T2) high asthma and CRSwNP are linked to eosinophils and cytokines, interleukin (IL)-4, IL-5, IL-13, while Type 2 low endotype involves Th17 pathways and neutrophilic inflammation." (PMID 41213931, 2025). "Th2 immune responses are characterized by the increased production of IL-4, IL-5, and IL-13, and have been associated with RV infection in asthma." (PMID 39941446, 2025). "IL-5 and IL-13 represent type-2-mediated eosinophilic inflammation, which has been implicated in airway remodeling in long-standing asthma." (PMID 41440978, 2025). "IL-13 is a typical Th2 cytokine that is up-regulated in asthma patients and is causal for airway disease." (PMID 40589325, 2025). "T2 asthma is linked to atopy and eosinophilic inflammation, which involves cytokines such as IL-4, IL-5, IL-9, and IL-13." (PMID 41318536, 2025). "As importantly, the epigenetic network associated with asthma development in at‐risk neonates born to mothers with low IFN‐γ:IL‐13 was enriched in differentially methylated CpG sites that mapped to microbe‐responsive elements." (PMID 39625247, 2025). "Asthma pathology is heterogeneous; a major subtype is type 2 (T2) high asthma, which is driven by T helper 2 (Th2) lymphocytes and T2 cytokines (IL-4 and IL-13), and is often associated with eosinophilia and elevated immunoglobulin E (IgE)." (PMID 40843371, 2025). "During RSV infection, the activation of the uric acid pathway increases the expression of TSLP, which in turn activates ILC2s to produce IL-13, promoting a Th2-type immune response associated with the development of asthma." (PMID 40636260, 2025). "We next tested the role of MTOR using this time-dependent IL-13 model in the development and maintenance of airway mucous cell metaplasia associated with severe asthma." (PMID 40446022, 2025). "The inflammation in bronchial tubules of lungs worsens the asthma which is also associated with Th2 cytokines release such as IL‐4 and IL‐13, that resultantly involve in remodeling of markers related to M2 macrophages." (PMID 39830909, 2025). "Periostin expression in the epithelium is increased by the T2-cytokine, IL-13, and in asthma has been associated with both increased airway eosinophils and mucus secretion." (PMID 40133927, 2025). "Lower sputum IL-13 levels have demonstrated better diagnostic accuracy than both sputum eosinophils and FeNO in identifying well-controlled asthma, suggesting a role as a monitoring biomarker in the assessment of asthma control." (PMID 40863432, 2025). "Cytokine activity is closely associated with asthma, as cytokines like IL-4, IL-5, and IL-13 can promote mucus overproduction and bronchial hyperresponsiveness, which are symptoms of asthma." (PMID 40266878, 2025). "In childhood asthma, specific epigenetic alterations, such as acetylation of the Foxp3 and IL13 genes, have been shown to influence immune regulation, further linking early-life epigenetic modifications to an increased susceptibility to asthma." (PMID 40806756, 2025). "Several genes within the cytokine gene cluster on chromosome 5, specifically IL3, IL4, CSF2, TSLP, IL5, RAD50, and IL13, are recognized as potential asthma susceptibility genes due to their roles in inflammatory regulation among sensitized asthma patients." (PMID 41001556, 2025).
asthma (continued). "The underlying pathology in most asthma cases involves type 2 inflammation, predominantly orchestrated by T helper type 2 (Th2) cells secreting interleukins (IL‐4, IL‐5, and IL‐13), eosinophils, and mast cells, among other factors." (PMID 41200848, 2025). "Polymorphisms in genes for alarmins (TSLP and IL‐33) and type 2 cytokines (IL‐4 and IL‐13) influence asthma risk and severity, although many genetic contributors remain unidentified." (PMID 40679787, 2025). "Asthma is a persistent inflammatory condition of the airways linked to type 2 cytokines, such as IL-4, IL-5, and IL-13." (PMID 40558541, 2025). "TL1A has been implicated in inducing the expression of IL-13 by innate lymphoid cells, leading to mucus production, airway inflammation, and fibrosis, all of which are characteristic features of asthma." (PMID 39962262, 2025). "Imbalances in IL-4 and IL-13 are implicated in the development of inflammatory diseases like UC and asthma." (PMID 40333150, 2025). "We investigated the association of two polymorphisms in the IL13 gene [rs1800925 (c.-93+487C>T), and rs20541 (p.Gln144Arg)] with asthma susceptibility among Sudanese patients." (PMID 39744511, 2025). "Only recently were ILC2 defined, the importance of the alarmins explored, and the direct association with ILC2, and their IL-5 and IL-13 production, with allergy and asthma determined." (PMID 40821845, 2025). "Th2 cells are pathogenic in asthma because they produce high amounts of the prototypical type 2 cytokines IL-4, IL-5, IL-9, and IL-13." (PMID 41145900, 2025). "Type 2 cytokines interleukin (IL)-4 and IL-13 induce mucus production in the airways, with IL-13 playing a significant role in excessive mucus production associated with asthma." (PMID 40709340, 2025). "Asthma often begins in childhood (childhood-onset asthma) and is often associated with exaggerated type 2 immunity, involving the production of the prototypical type 2 cytokines IL-4, IL-5, and IL-13." (PMID 41145900, 2025). "Among the highly upregulated proteins, IL-13 strongly correlated with IL-5, both linked to Th2-type immune responses and associated with allergic inflammation, asthma, and other viral lung infections like influenza and RSV (respiratory syncytial virus)." (PMID 40557167, 2025). "For example, cytokines like interleukin‐13 (IL‐13), which are crucial in asthma pathogenesis, have also been implicated in CD." (PMID 40735257, 2025). "In contrast, in a 17-centre prospective cohort study of infants with severe bronchiolitis, serum periostin induced by type 2 inflammatory cytokines (e.g., interleukin IL-4 and IL-13) was associated with asthma risk by age 6 years." (PMID 40852413, 2025). "By targeting immunoglobulin E (IgE), thymic stromal lymphopoietin (TSLP), and specific cytokines such as IL-5, IL-4, and IL-13, biologics offer more precise and personalized treatment in patients with severe asthma and associated comorbidities." (PMID 41156259, 2025). "Estrogenic EDCs like BPA and phthalates skew the immune balance toward Th2 polarization by increasing IL-4, IL-5, and IL-13 production, thereby heightening the risk of allergic diseases, including asthma and atopic dermatitis." (PMID 41020825, 2025). "IL-17A, primarily associated with neutrophilic inflammation, is implicated in severe and steroid-resistant asthma; it enhances proinflammatory mediator production and works with IL-13 to amplify airway inflammation." (PMID 41256924, 2025). "For instance, Th2-driven asthma, which is characterized by elevated levels of IL-4 and IL-13, is associated with histone hyperacetylation at H3K9 and trimethylation at H3K4." (PMID 40806756, 2025). "Previous studies have shown that PI3K inhibitors suppress pathological features associated with asthma, including chemokine secretion by activated eosinophils, increased levels of IL-5 and IL-13 in the bronchi, and eosinophil infiltration in lung tissue." (PMID 39940325, 2025).
asthma (continued). "Interleukin-13 (IL-13) is a cytokine mainly associated with helminth infections and allergic inflammation, including asthma and allergic rhinitis." (PMID 40003307, 2025). "It has been observed that the genes susceptible to asthma are clustered on the long arm of chromosome-5, where the interleukin-13 (IL-13) is located." (PMID 39744511, 2025). "The most common asthma variant in children, T2-high asthma, is characterized by atopy, eosinophilic inflammation, elevated Th2 cytokines (IL-4, IL-5, and IL-13), and leukocyte recruitment driven by CD4 + T-cells, mast cells, and eosinophils." (PMID 40806181, 2025). "IL-4 and IL-13 are key asthma pathogenetic cytokines and are both implicated directly in bronchial inflammation and airway remodeling." (PMID 40283665, 2025). "Recent data indicate that the asthma-associated cytokines IL-4 and IL-13 can reprogram lung-innervating nociceptor neurons to adopt a pro-allergic phenotype 24." (PMID 39229121, 2025). "Recently, this device was implemented to characterize the mucus on live human airway epithelial cell cultures in situ for the first time and quantify the change in mucus rheology with IL-13-induced inflammation associated with asthma." (PMID 38721267, 2024). "Th2 cells are best known for producing IL-4, IL-5, and IL-13 and are associated with host defenses against parasites and involvement in allergies and atopic diseases such as asthma." (PMID 39481080, 2024). "The sensitised mice exhibited an increased expression of the Th2-like and asthma-associated cytokines, IL-4, IL-5, and IL-13, as well as mRNA encoding for pro-inflammatory TNF-α and the Th1 cytokine IFN-γ." (PMID 38765484, 2024). "Allergic inflammation, which is the pathogenesis of allergic rhinitis and asthma, is associated with disruption of the airway epithelial barrier due to the effects of type 2 inflammatory cytokines, i.e. interleukin-4 and interleukin-13 (IL-4/13)." (PMID 38687777, 2024). "Recent advances in understanding asthma pathogenesis have made it clear that various cytokines, in addition to the atopy-associated Th2 cytokines (IL-4, IL-5, and IL-13), play crucial roles in the induction and regulation of airway inflammation." (PMID 39902293, 2024). "Briefly, as the induction of asthma is a complex topic, Th2-high asthma represents the mechanism of IL-4, IL-5, and IL-13 associated asthma, which induces roughly 50% of mild-to-moderate asthma and the majority of severe asthma inflammation." (PMID 39239645, 2024). "For instance, allergic asthma appears to offer protection through the IL-13 pathway, whereas severe asthma appears to be associated with severe COVID-19 outcomes through the ACE2 receptor pathway." (PMID 38750426, 2024). "As IL-13 is known to be associated with asthma, subjects using asthma medication were removed from the regression analysis." (PMID 38702427, 2024). "We focused on genes that correlated with one particular gene, MUC16, which encodes an IL13-induceable mucin thought to play a prominent role in asthma-associated mucus obstruction of the airway." (PMID 39294560, 2024). "Elevated levels of IL-13, IL-4, and IL-5 are particularly associated with asthma, contributing to airway hyperresponsiveness, eosinophil recruitment, and mucus production." (PMID 39902079, 2024). "Th2 cells promote airway inflammation by production of a range of cytokines including IL-4, IL-5, IL-9, IL-13 and IL-25, which together are responsible for the development of hallmark features of asthma." (PMID 39598682, 2024). "By blocking the action of cytokines such as IL-4, IL-5 and IL-13, biologics can help to reduce T2 inflammation and associated severe asthma symptoms, including exacerbations." (PMID 38453256, 2024). "Additional asthma therapies, also approved for children, use biologicals such as Omalizumab or Dupilumab which target IgE or asthma-associated cytokines such as IL-4 and IL-13, respectively." (PMID 38172451, 2024).